ERBB2 (erb-b2 receptor tyrosine kinase 2)
Diseases named in the same sentence as ERBB2 in open-access papers (continued):
Sharing a sentence is not in itself a finding about the gene and the disease.
breast cancer (continued). "This tumor subset has been known for almost 20 years as “HER2 positive” breast cancers (3+ by immunohistochemistry (IHC), or 2+ by IHC and ErbB2 amplification by fluorescent in situ hybridization (FISH))." (PMID 37561255, 2023). "Human epidermal growth factor receptor 2 (HER2)-positive breast cancer refers to the amplification of the ERBB2/neu proto-oncogene or the overexpression of the HER2 transmembrane receptor protein." (PMID 36673073, 2023). "FGFR4 and ErbB2 collaboratively regulate cyclin D1 expression, thereby promoting cell proliferation in breast cancer." (PMID 38077251, 2023). "HER2-enriched breast cancers are driven by ERBB2/HER2 gene amplification, and they grow faster than luminal cancers." (PMID 36982548, 2023). "We decided to study the KMT2C role in the context of mouse mammary tumours driven by the well-established breast cancer oncogenic drivers Erbb2/Neu, Myc and PIK3CAH1047R." (PMID 36933062, 2023). "The racial disparity in pCR rate varied across different breast cancer subtypes and was most profound among patients with HR-/ERBB2+ disease." (PMID 36995716, 2023). "Amplification or overexpression of ErbB2 has been observed in 30% of breast cancer patients, driving cell transformation and cancer development." (PMID 37990309, 2023). "More promising therapeutic avenues encompass the deployment of anti-ErbB2 antibodies, exemplified by trastuzumab, especially for HER2-positive breast cancer variants." (PMID 37762375, 2023). "NPC1 increase facilitates extracellular cholesterol uptake and is necessary for the invasion of ErbB2 expressing breast cancer spheroids and ovarian cancer organoids, indicating a regulatory role for NPC1 in the process." (PMID 37420029, 2023). "It was later reported that, in Her-2 overexpressing breast cancer cells, progranulin conferred resistance to trastuzumab by promoting ErbB2/Her-2 phosphorylation." (PMID 36980592, 2023). "Amplification of the ERBB2 gene results in HER2 overexpression, which has a central role in promoting carcinogenesis in breast cancer and is associated with poor prognosis in untreated patients." (PMID 37017812, 2023). "We also found a slight improvement in OS in ERBB2-low breast cancer, particularly in advanced TNBC, although the size of the difference is of questionable clinical relevance, with overlapping survival curves when plotted by stage and receptor status." (PMID 36821125, 2023). "Breast cancer disease is heterogeneous, with different molecular subtypes, including HER2-positive breast cancer, which is defined as a type that has amplified or overexpressed the HER2 gene (or ErbB2)." (PMID 36602979, 2023). "As recent studies in HER2low (HER2 score 1+ or 2+) breast cancer suggest, combined detection of ERBB2 by FISH and NGS can be used for subtyping tumors with ERBB2 alterations or amplifications." (PMID 38138928, 2023). "Using two different CAR NK-92 systems targeting PD-L1 or ErbB2 molecules, we demonstrate that human NK cells survive in the zebrafish environment and retain specific cytotoxicity against metastatic breast cancer cells." (PMID 37885894, 2023). "Missing ER, PR, and/or ERBB2 status is associated with biases in estimating SEER incidence rates and survival probabilities for specific breast cancer subtypes." (PMID 37615986, 2023). "Amplification of the ERBB2 gene, encoding human epidermal growth factor receptor 2 (HER2), occurs in approximately 15% of primary breast cancers (PBC) and causes overexpression of the protein kinase receptor HER2." (PMID 37968696, 2023). "ErbB2/HER2 (human epidermal growth factor receptor 2) is an oncogenic tyrosine kinase receptor overexpressed in 25% of primary human breast cancer cases as a result of ErbB2 gene amplification or enhanced expression." (PMID 36912768, 2023). "We demonstrate that Vangl2 is critical for efficient metastasis but dispensable for primary tumor growth in ErbB2-induced mouse mammary tumors." (PMID 37147680, 2023).
breast cancer (continued). "High CDKN1B expression predicts sensitivity to hormone therapies and chemotherapy in luminal breast cancer patients, while its downregulation predicts resistance to radiotherapy and anti‐ERBB2 therapies." (PMID 37039257, 2023). "ERBB2 is a known proto-oncogene that plays an important role in human malignancies and is amplified or overexpressed in 30% of human breast cancers." (PMID 37768281, 2023). "EphA2 is also overexpressed and associated with poor prognosis in breast cancer, where it amplifies oncogenic signalling of the RTK erbB2 (HER2), and the loss of EphA2 in the mammary epithelium of mice slowed down tumour development and metastasis." (PMID 36830852, 2023). "Various agents that target ErbB2, including trastuzumab, pertuzumab, and lapatinib, have been widely used—and shown to be effective—in the treatment of patients with ErbB2-positive breast cancer." (PMID 37508418, 2023). "The same breast cancer model was generated by crossing transgenic ErbB-2(KI)-ErbB-2 mice with PTENf/f and MMTV-cre mice." (PMID 37291517, 2023). "A19 binding studies revealed that this antibody recognizes the N-glycan epitope on Erb-b2 (Erb-b2 receptor tyrosine kinase 2) that is expressed by many different breast cancer and ovarian cancer cell lines." (PMID 36977072, 2023). "In breast cancer, the heterodimerization of ErbB2 and Axl induces EMT and therapy resistance by regulating Akt and Mek signaling." (PMID 37746265, 2023). "Plexin-B1–mediated activation of RhoA/C is a key pathway promoting metastasis in ErbB2-mouse models of breast cancer." (PMID 36936664, 2023). "For patients with ERBB2-positive cancer, there was a 10-fold increase in the use of trastuzumab-based therapy for early breast cancer from 2011 to 2021 in China." (PMID 37389867, 2023). "Further improvements are needed in molecular stratification of ERBB2 expression to understand the clinical significance of ERBB2-low breast cancer and identify patients who can benefit from novel therapies." (PMID 36821125, 2023). "This glycolytic phenotype is similar to ErbB2 lung metastatic murine breast cancer cells that generate ~20% of ATP by oxidative phosphorylation." (PMID 36805760, 2023). "Trastuzumab (Tz), an antibody targeting ERBB2, has significantly improved the prognosis for breast cancer (BCa) patients with overexpression of the ERBB2 receptor." (PMID 37367744, 2023). "Our study found that Black patients diagnosed with TNBC and ERBB2+ breast cancer had more refractory disease to NACT, whereas those of other races and ethnicities, especially Asian patients, had more sensitive disease." (PMID 37991763, 2023). "We can conclude that although patients with HR–/ERBB2+ breast cancer had a short interval for developing CBC, the incidence was lower than for other subtypes." (PMID 38100108, 2023). "Knockdown of LDHA in ErbB2-transformed mouse mammary tumor cells inhibited their tumorigenicity, suggesting that ErbB2 induces mammary tumorigenesis through, at least in part, LDHA." (PMID 37444501, 2023). "ERBB2 amplification was found in 6% of total tumors and most amplified in gastric and breast cancers (11% and 10%, respectively)." (PMID 37298484, 2023). "Examples include the use of imatinib (Gleevec) for chronic myelogenous leukemia, crizotinib and other anaplastic lymphoma kinase (ALK) inhibitors for non-small-cell lung cancers, and trastuzumab and lapatinib for ERBB2/HER2 amplified breast cancers." (PMID 36809237, 2023). "Trastuzumab in various forms in combination with chemotherapy has been successful in targeting ERBB2 overexpression in ERBB2+ breast cancer and improving survival as a standard first-line therapy for more than a decade." (PMID 37359373, 2023).
breast cancer (continued). "According to the expression of hormone receptors (HRs) and ERBB2 gene amplification, breast cancer can be categorized into three subtypes." (PMID 37237509, 2023). "According to the classification of breast cancer into ER and PR expression and HER2/ERBB2 gene amplification, different treatment strategies are applied." (PMID 37213283, 2023). "MiR-1296-5p has been reported to decrease ERBB2-positive breast cancer and exerts a tumor-suppressive function in breast cancer." (PMID 37187897, 2023). "ERBB2 (erb-b2 receptor tyrosine kinase 2), also known as HER2, showed spatial patterns in most breast cancer tissue samples, and particularly, was highly expressed in the tumor region, as reported to be overexpressed in ∼30% of human breast cancers." (PMID 36243975, 2023). "Breast cancer is classified into three types based on histological characteristics: endocrine-dependent breast cancer, erb-b2 receptor tyrosine kinase 2 (HER2)-positive breast cancer, and triple-negative breast cancer (TNBC)." (PMID 37287817, 2023). "One of these is Rac 1 whose ability to regulate actin reorganization needed for the growth factor-induced formation of membrane ruffles depends on cholesterol and which is needed for the ErbB2-induced breast cancer cell invasion." (PMID 37420029, 2023). "All ERBB2-amplified breast cancers were HER2-positive (over-expression) clinically, with most being ER- and progesterone receptor (PR)-negative and were diagnosed evenly with early- (Group 1 and Group 2A, n = 9) and late-stage disease (n = 7)." (PMID 37760445, 2023). "Here, we provide a proof‐of‐principle validation of EV‐RNA and cfDNA isolated through ONCE as informative analytes for detecting the ERBB2/HER2 biomarker in a cohort of early‐stage breast cancer (BrCa) patients with tissue‐defined HER2 status." (PMID 38046436, 2023). "In mouse models, HK2 has been shown to be essential for initiation and continued maintenance of K-Ras–driven lung cancer and ErbB2-driven breast cancer." (PMID 37343102, 2023). "The NCT02568839 trial, conducted at nine locations in Sweden with 202 participants, compared the efficacy of two neoadjuvant treatment methods for ERBB2-positive breast cancer." (PMID 38352694, 2023). "ErbB2 has been shown to be involved in the progression and development of many different tumors, especially breast cancer." (PMID 36880347, 2023). "Patients with ERBB2-overexpressing breast cancer have lower overall survival rates and shorter disease-free intervals than patients whose cancer does not overexpress ERBB2." (PMID 37859946, 2023). "These combination treatment strategies can improve clinical outcomes in HR+/HER2+ or ERBB2-mutant breast cancer, potentially overcoming resistance to ET arising from crosstalk between the ER and HER2 signaling pathways." (PMID 37258523, 2023). "Lapatinib is an oral drug that is approved globally in combination drug treatments for metastatic, ErbB2-positive breast cancer." (PMID 37581931, 2023). "After PPARγ was identified as a mature positive regulator of adipogenesis and lipid storage in 2013, inhibition of PPARγ was reported to reduce aldehyde dehydrogenase (ALDH) activity in ERBB2-positive breast cancer cells." (PMID 37251321, 2023). "Both breast cancer and stomach cancer have received complete confirmation of the carcinogenic effect of ERBB2 amplification." (PMID 37525498, 2023). "In studies suggesting that PPARg has tumour-promoting effects, T0070907 has been proven to inhibit the formation of ERBB2-positive breast cancer cells into tumours, the growth of hepatocellular carcinoma cells and the brain metastasis of melanoma." (PMID 36681687, 2023). "To assess any association between the expression of TNC and CCL2, we analyzed RNA sequencing data from 77 HER2+/ERBB2+ breast cancer patients available from The Cancer Genome Atlas." (PMID 37176074, 2023).
breast cancer (continued). "What is the association of PIK3CA mutations, response to therapy, and outcome by hormone receptor (HR) status and intrinsic subtype among patients with ERBB2/HER2-positive early breast cancer (EBC) treated in a clinical trial?" (PMID 38117494, 2023). "A study on the effects of a combined treatment with 5-fluorouracil (5-FU) and apigenin has shown cell growth inhibition and apoptosis induction via the downregulation of ErbB2 expression and Akt signaling in human breast cancer cells." (PMID 38203418, 2023). "We found that these candidate genes were enriched in ErbB2 pathway, cell cycle and breast cancer signaling pathways, which were key in BCa progression." (PMID 36632463, 2023). "It is well known that 25% of early-stage and 75% of late-stage ERBB2+ breast cancer is resistant to trastuzumab." (PMID 37359373, 2023). "It has been reported that inhibition of the PPARG pathway reduces the aldehyde dehydrogenase positive population in ERBB2-positive breast cancer cells supporting its role in development of BC36." (PMID 37607964, 2023). "Na+, HCO3- cotransporter NBCn1 (Slc4a7) is increased in ErbB2-induced breast cancer tissue compared to normal, and disrupting NBCn1 expression delays ErbB2-induced breast cancer development." (PMID 36632452, 2023). "ERBB2 is expressed at a low level and almost undetectable in normal tissues, but it is found to be overexpressed in multiple tumors, such as breast cancer, ovary carcinoma, prostate carcinoma, and non-small-cell lung cancer." (PMID 37333450, 2023). "The first mAb approved for solid tumors was trastuzumab (anti-ERBB2) in 1998 for HER2-positive breast cancer." (PMID 37509390, 2023). "Oestrogen receptor positive (ER+)/ human epidermal growth factor receptor 2 positive (HER2+) breast cancer is strongly influenced by the HER2-E subtype and erbB2, which results in resistance to endocrine therapy and a higher probability of recurrence." (PMID 37569598, 2023). "When PPARγ1 is acetylated at the conserved lysine motif (K154/155), it promotes lipid synthesis in ErbB2-positive breast cancer cells." (PMID 36647790, 2023). "This suggests that for selected ERBB2-positive breast cancer patients, neoadjuvant treatment can be de-escalated to T-DM1 monotherapy without compromising efficacy." (PMID 38352694, 2023). "Breast cancer cells that make too much HER2/ERBB2 spread faster but are also more likely to respond to HER-specific chemo and immunotherapy, with mutations in MUC4 known to associate with upregulated ERBB proteins, observed in the Indian cohort." (PMID 37091785, 2023). "Some researchers have shown this breast cancer cell line as a HER2 subtype because only ErbB-2 is expressed in experiments completed via PCR, culture assays, or other methods." (PMID 38137912, 2023). "In order to evaluate immune infiltration, we immunohistochemically stain sections of the murine ErbB2-induced breast carcinomas for CD3+ T cells, CD19+ B cells, and F4/80+ macrophages." (PMID 37098526, 2023). "Previous studies showed selective recognition and elimination of ErbB2-positive breast carcinoma and glioblastoma cells with high target antigen expression levels by NK-92/5.28.z cells." (PMID 37662907, 2023). "The pH values we record from the tumor microenvironment of untreated ErbB2-induced breast carcinomas are high relative to our previous measurements of approximately 6.7 from carcinogen-induced tumors." (PMID 37098526, 2023). "ERBB2 amplification and protein overexpression play variable roles in diverse cancers such as breast cancer (BC), esophagogastric and gastric cancer (GC), ovarian cancer, UBC, extrahepatic cholangiocarcinoma, lung cancer, and colon cancer." (PMID 37173881, 2023). "ERBB2/HER2 overexpression or amplification defines the clinical ERBB2/HER2-positive breast cancer (BC) subtype." (PMID 38117494, 2023).
breast cancer (continued). "In 2 cases, the presence of ERBB2 duplication prompted additional immunohistochemical analysis with mammaglobulin, GATA3, and GCDFP, which ultimately led to diagnosis of HER2 positive breast carcinoma." (PMID 36933203, 2023). "Approximately 15% of breast cancers harbour an amplification of the ERBB2 gene and/or an overexpression of the HER2 protein and are thus classified as HER2-positive." (PMID 36900178, 2023). "The high PPV of ERBB2 CNG for HER2-positivity in breast cancer is particularly relevant as tissue biopsies can be a challenge for patients with bone predominant disease." (PMID 35126865, 2022). "Lovastatin also modulates PM rigidity and fluidity, promoting endocytic degradation of the tyrosine kinase receptor ErbB2 and thus synergizing with the tyrosine kinase inhibitor lapatinib to impair ErbB2-positive breast cancer growth." (PMID 36439249, 2022). "ERBB2 amplification/HER2 overexpression is also found in 10% of ER+ breast cancers and the current standard of care for ER+/HER2+ is a combination of anti-ER and HER2 inhibitors." (PMID 35774123, 2022). "Altogether, our data strongly suggest that upregulated PTPRO in ERBB2-positive breast cancer cells can enhance lapatinib sensitivity." (PMID 35431974, 2022). "Overexpression of HER2, primarily as a result of amplification of ERBB2, identifies an aggressive breast cancer phenotype with a high risk for metastatic disease to visceral organs and the central nervous system." (PMID 35126865, 2022). "More trials are assessing novel monoclonal antibodies (MoAbs), small molecule tyrosine kinase inhibitors (TKIs), and antibody drug conjugates (ADCs) as the third-line and beyond therapy for ERBB2-positive advanced breast cancer." (PMID 36159262, 2022). "For example, trastuzumab is a monoclonal antibody which was first approved to treat patients with HER2+ breast cancer, and was subsequently approved in ERBB2-amplified NSCLC41 and HER2-overexpressing gastric adenocarcinoma." (PMID 35849877, 2022). "The human epidermal growth factor receptor (HER)-2 enriched breast cancer is characterized by the overexpression of the ERBB2 oncogene, which leads to an aggressive tumoral phenotype." (PMID 35884904, 2022). "Regarding the effect of ERBB2 fusions on the efficacy of targeted drugs, there are also related reports on colorectal cancer and breast cancer." (PMID 36276102, 2022). "RTK families that have been shown to translocate to the nucleus include ErbB2 in breast cancer, FGFR1 in medulloblastoma, and VEGFR1 in lymphoma." (PMID 36214254, 2022). "Targeting ErbB2-overexpressing cells was performed in nine patients with breast cancer at a site of metastasis in the skin, lungs, lymph nodes, liver, and chest wall and in two patients with melanoma colorectal cancers." (PMID 35744957, 2022). "In trastuzumab-resistant ErbB2-positive breast cancer cells, higher glycolytic activity is mediated by heat shock factor 1 and LDHA." (PMID 35328602, 2022). "We employed a collection of genes associated to endocrine therapy resistance in breast cancers expressing estrogen receptor (ESR1) and ERBB2 (HER2) and identified a significant enrichment (NES 1.56)." (PMID 36359853, 2022). "ErbB3 over-expression and the consequent activation of PI3K/Akt signaling lead to the development of resistance to tyrosine kinase inhibitors such as gefitinib in ErbB2 over-expressed breast cancers." (PMID 35319011, 2022). "As a heterogeneous disease, breast cancer can be divided into 3 major subtypes in terms of molecular markers for estrogen or progesterone receptors and human epidermal growth factor 2 (ERBB2; formerly HER2)." (PMID 36671425, 2022). "Breast cancer also contains several molecular subtypes, including HR+/ERBB2−, ERBB2+ as well as triple-negative." (PMID 36936274, 2022).